GPR84 (G protein-coupled receptor 84)
Description:
G protein-coupled receptor that responds endogenously to dietary fatty acids or nutrient, specifically medium-chain free fatty acid (FFA) with carbon chain lengths of C9 to C14. Capric acid (C10:0), undecanoic acid (C11:0) and lauric acid (C12:0) are the most potent agonists. In immune cells, functions as a pro-inflammatory receptor via 6-OAU and promotes the expression of pro-inflammatory mediators such as TNFalpha, IL-6 and IL-12B as well as stimulating chemotactic responses through activation of signaling mediators AKT, ERK and NF-kappa-B (By similarity). In addition, triggers increased bacterial adhesion and phagocytosis in macrophages and regulates pro-inflammatory function via enhancing NLRP3 inflammasome activation (By similarity). Also plays an important role in inflammation by modulating neutrophil functions (By similarity). Mechanistically, promotes neutrophil chemotaxis, reactive oxygen species (ROS) production and degranulation via LYN-AKT/ERK pathway (By similarity). To regulate ROS, communicates with the two formyl peptide receptors FPR2 and FPR1 to control the NADPH oxidase activity in neutrophils.
Synonyms: EX33; GPCR4
Tractability: Small molecule: a drug acting on it is in phase 2 or 3 trials; a structure with a bound ligand is known; a high-quality ligand is known; it belongs to a druggable protein family. Antibody: UniProt places it where antibodies can reach, with high confidence; its Gene Ontology location is reachable by antibodies, with high confidence; UniProt predicts a signal peptide or a membrane-spanning region. PROTAC: its protein half-life has been measured; a small molecule that binds it is known.
Target class: Family A G protein-coupled receptor; Membrane receptor
Gene: Protein-coding gene on chromosome 12 (54,362,445 to 54,364,487, reverse strand). Ensembl gene ENSG00000139572.
Subcellular location: Cell membrane
Pathways (Reactome):
Immune System: Neutrophil degranulation
Signal Transduction: G alpha (s) signalling events
Gene Ontology:
Molecular function: protein binding; urotensin II receptor activity; G protein-coupled receptor activity
Biological process: neuropeptide signaling pathway; G protein-coupled receptor signaling pathway
Cellular component: plasma membrane; receptor complex; specific granule membrane; tertiary granule membrane; membrane
Genetic constraint (gnomAD): Loss-of-function variants: 11 observed, 20.74 expected, observed/expected ratio (o/e) 0.53, 90% interval 0.33 to 0.88. The synonymous counts are far from expectation, so gnomAD's model fits this gene poorly and the ratio says little. Missense variants: 421 observed, 523.17 expected, observed/expected ratio (o/e) 0.8, 90% interval 0.74 to 0.87. Synonymous variants: 162 observed, 208.65 expected, observed/expected ratio (o/e) 0.78, 90% interval 0.68 to 0.88.
Homologues: Orthologues: chimpanzee GPR84 (99% identical), macaque GPR84 (95% identical), pig GPR84 (90% identical), guinea pig GPR84 (84% identical), rat Gpr84 (84% identical), dog GPR84 (82% identical), zebrafish gpr84 (48% identical), Caenorhabditis elegans dop-1 (20% identical). Paralogues in human: HTR4 (18% identical), CHRM1 (18% identical), DRD4 (17% identical), HTR1D (17% identical), HTR1A (17% identical), GPR52 (17% identical), CHRM5 (17% identical), DRD3 (17% identical), TAAR5 (17% identical), CHRM3 (16% identical), GPR21 (16% identical), HRH3 (16% identical), and 13 more.
Diseases named in the same sentence as GPR84 in open-access papers:
GPR84 is named in the same sentence as 81 diseases in open-access papers, as found by Europe PMC text mining. Sharing a sentence is not in itself a finding about the gene and the disease. The quoted sentences say what the papers report.
Obesity (9 papers, 2018 to 2025). Accumulation of substantial excess body fat. "Therefore, HFD‐fed Gpr84−/− mice exhibited metabolic benefits, such as improvement of inflammation, as well as anti‐obesity and loss of WAT weights." (PMID 39512839, 2024). "In summary, this study confirmed elevated levels of FFA C8:0 in obesity can up-regulate the transcription factor KLF7 through fatty acid receptor GPR84." (PMID 37170248, 2023). "In humans, the GPR84 expression levels in adipose tissue from obese and nondiabetic subjects were positively correlated with low-calorie diet intervention (Gene Expression Omnibus [GEO] GSE95640), suggesting a beneficial role for GPR84 in obesity." (PMID 37856216, 2023). "Our data showed that TriC10 intake, administration of TriC10 and C10:0, and C10:0 supplementation exerted inhibitory effects on HFD-induced obesity and improved glucose homeostasis by GPR84-mediated GLP-1 secretion in in vivo and in vitro studies." (PMID 35399667, 2022). "In this study, we found that decanoate is clearly functionable to regulate glucose homeostasis by GLP-1 secretion via GPR84, improves insulin sensitivity, and prevents obesity." (PMID 35399667, 2022). "Histological assessment of HFD-fed WT and KO mouse liver tissue revealed that Gpr84−/− mice were more resistant to the development of obesity-induced NAFLD." (PMID 32728158, 2020). "Thus, MCT (TriC10) intake efficiently prevented obesity, and its effects were partially mediated by GPR84." (PMID 39512839, 2024). "Our findings may be instrumental for future studies on drug development with GPR84 as a potential target, thereby offering new avenues for the treatment of metabolic disorders like obesity and type 2 diabetes." (PMID 39512839, 2024). "Medium‐chain triglyceride (C10:0) intake suppressed obesity, and improved plasma glucose and lipid levels, and increased plasma GLP‐1 levels in wild‐type mice; however, these effects were partially attenuated in Gpr84‐deficient mice." (PMID 39512839, 2024). "Medium-chain FA levels change under various metabolic disturbances such as starvation, feeding, cold exposure, type 1 diabetes, and obesity, indicating that GPR84 activity may vary under these conditions." (PMID 37856216, 2023). "Therefore, our findings could pave the way for research on developing drugs or supplements targeting GPR84, with potential applications in treating metabolic disorders such as obesity and type 2 diabetes." (PMID 39512839, 2024). "An animal study based on male mice found that decanoic acid intake can effectively prevent obesity and promote glucagon-like peptide-1 (GLP-1) secretion through the MCFA receptor GPR84 to enhance glucose tolerance and improve insulin resistance." (PMID 39839274, 2024). "For obesity‐induced T2DM, several class A orphan GPCRs, including GPR21, GPR35, GPR84, and GPR132, are suggested to play an active role in the developmental processes of T2DM." (PMID 36721851, 2023). "In this study, we determined the expression levels of GPR84, KLF7, IL-6, p21 in tumor tissues of patients with PCa and obesity with primary PCa tumor-bearing mouse model." (PMID 37170248, 2023). "We specifically chose GPR119, GPR84, GPR40, and TGR5 to use as a combined stimulus since these receptors were up-regulated in obesity and RYGB, and as GPR119 and GPR40 have been shown to exhibit synergistic effects on GLP-1 secretion." (PMID 30336615, 2018). "Additionally, C10:0 stimulation promoted GLP-1 secretion via GPR84 in STC-1, enhanced glucose tolerance through GPR84-mediated GLP-1 secretion, and showed resistance to high-fat diet (HFD)-induced obesity in mice." (PMID 35399667, 2022).
acute myeloid leukemia (8 papers, 2016 to 2023). Acute myeloid leukemia (AML) is a group of neoplasms arising from precursor cells committed to the myeloid cell-line differentiation. "In a study of acute myeloid leukemia, activated GPR84 can promote disease resistance through the Wnt /β-catenin axis, which targets and modulates the expression of factor KLF7 in non-small cell lung cancer cells." (PMID 37170248, 2023). "GPR84 is a fatty-acid binding protein involved in fibrosis and is also essential in the maintenance of cancer stem cells in acute myeloid leukemia." (PMID 34359681, 2021). "We have recently reported essential roles for G protein-coupled receptor 84 (GPR84) and G protein subunit Gαq in the maintenance of cancer stem cells in acute myeloid leukemia." (PMID 27187360, 2016). "Consistent with our results, GPR84 has been proposed to function as a pro-inflammatory GPCR, which may play a role in reflux esophagitis, IBD, neuropathic pain, fibrosis, and acute myeloid leukemia." (PMID 34912006, 2022). "Our functional study shows that GPR84 depletion impairs LSC function and inhibits the development of an aggressive and drug-resistant subtype of acute myeloid leukemia (AML)." (PMID 27187360, 2016). "GPR84 is found to be upregulated in AML leukemic stem cells and expression of this GPR member is correlated with significantly overall survival of patients diagnosed with acute myeloid leukemia (AML)." (PMID 38116002, 2023).
ulcerative colitis (8 papers, 2020 to 2024). An inflammatory bowel disease involving the mucosal surface of the large intestine and rectum. "Here we demonstrate that GPR84 is highly upregulated in inflamed colon tissues of active ulcerative colitis (UC) patients and dextran sulfate sodium (DSS)-induced colitis mice." (PMID 34912006, 2022). "Our present study adds to these findings, highlighting differences of naturally occurring agonists not only activating GPR84 but also HCA3, a receptor often co-occurring with GPR84 and also found overexpressed in patients with ulcerative colitis." (PMID 32102673, 2020). "This is especially crucial since recent clinical trials have e.g. explored the potential of ligands blocking GPR84 function for the treatment of ulcerative colitis." (PMID 32102673, 2020). "Inflammatory colon tissue from patients who suffered from ulcerative colitis is filled with large numbers of GPR84-positive macrophages, whose involvement in the inflammatory response may depend on the activation of NLRP3 inflammasome." (PMID 36177003, 2022). "GPR84 is positively correlated with ulcerative colitis in patients." (PMID 34912006, 2022). "Because GPR84 transcript is up‐regulated in many pro‐inflammatory conditions, potential therapeutic opportunity in targeting this receptor in inflammatory conditions, including ulcerative colitis and fibrotic diseases, has been suggested." (PMID 32869860, 2022). "A recent study showed that GPR84 is highly expressed in the inflamed colon tissues of active ulcerative colitis (UC) patients and dextran sulfate sodium (DSS)-induced colitis mice, and that the knockout of GPR84 could help mice resist the development of colitis induced by DSS." (PMID 37835607, 2023). "Indeed, the best characterized high-affinity GPR84 antagonist, GLPG1205, has been, and is being, assessed clinically in both ulcerative colitis and idiopathic pulmonary fibrosis." (PMID 35427647, 2022).
diabetes (7 papers, 2018 to 2024). "An increase in GPR84 is seen in diabetes, atherosclerosis, and other diseases associated with inflammation." (PMID 34943862, 2021). "In accordance with this observation, a growing body of evidence supports a regulatory role of GPR84 in macrophage-mediated inflammation in lung injury processes, kidney fibrosis, diabetes, and the central nervous system." (PMID 38349405, 2024). "Available studies on GPR84 in cardiometabolic syndrome show that it has a proinflammatory role in the processes of diabetes and atherosclerosis." (PMID 34943862, 2021). "In addition, activation of GPR84 is thought to diminish release of adiponectin, a protein hormone that protects against insulin resistance/diabetes, and GPR84 expression levels are increased by hyperglycemia." (PMID 33960725, 2021). "PBI-4547, mainly through its antagonistic effects on GPR84 activity, provided protection against NAFLD and diabetes, highlighting the potential of this drug in this rapidly growing indication." (PMID 32728158, 2020). "Considering that GPR84 has been claimed as a metabolic GPCR, we wanted to evaluate how its expression was regulated in two important metabolic diseases where inflammation plays a key role: diabetes and atherosclerosis." (PMID 29973940, 2018).
idiopathic pulmonary fibrosis (7 papers, 2019 to 2022). Idiopathic pulmonary fibrosis (IPF) is a nonneoplastic pulmonary disease that is characterized by the formation of scar tissue within the lungs in the absence of any known cause. "GPR84 antagonists are currently under investigation in several disease areas, including pulmonary fibrosis and type 2 diabetes." (PMID 32316235, 2020). "In the case of GPR84, currently a target for the treatment of idiopathic pulmonary fibrosis, recent times have seen the description of novel orthosteric and allosteric agonists." (PMID 30755705, 2019). "Expression of GPR84 is strongly up regulated in immune cells in a range of pro‐inflammatory settings and clinical trials to treat idiopathic pulmonary fibrosis are currently ongoing using ligands with differing levels of selectivity and affinity as GPR84 antagonists." (PMID 32869860, 2022). "By stimulating fibrosis, GPR84 may have a deleterious role in fibrotic disease, including pulmonary fibrosis." (PMID 33955686, 2021). "Moreover, GLPG1205, a nanomolar potency GPR84 antagonist, has demonstrated reduced lung fibrosis in two mouse models in a therapeutic setting." (PMID 32316235, 2020). "Furthermore, in a bleomycin‐induced mouse model of pulmonary fibrosis, treatment with PBI‐4050, described as a GPR84 modulator and GPR40 agonist, caused a 47% reduction of histological lesions in the lung (compared with vehicle), supporting a role for GPR84 in fibrotic disease." (PMID 33960725, 2021).
Insulin resistance (7 papers, 2020 to 2024). Increased resistance towards insulin, that is, diminished effectiveness of insulin in reducing blood glucose levels. "HFD‐induced glucose intolerance and insulin resistance were significantly exacerbated in HFD‐fed Gpr84−/− mice compared with wild‐type mice." (PMID 39512839, 2024). "We assumed that aged GPR84-KO mice have peripheral insulin resistance; thus, a hyperinsulinemic-euglycemic clamp study to delineate the tissues responsible for decreased insulin sensitivity would be necessary." (PMID 37856216, 2023). "Untreated Gpr84−/− mice HOMA-IR and disposition indices were also significantly improved compared to WT mice, suggesting that GPR84 is important in insulin resistance and in the control of glycemia, respectively." (PMID 32728158, 2020). "GPR84 has been demonstrated to be involved in the regulation of energy metabolism mediated by the secretion of insulin and inflammatory responses related to insulin resistance." (PMID 36368953, 2022). "Therefore, GPR84 might play a crucial role during the development of skeletal muscle insulin resistance." (PMID 36368953, 2022). "Indeed, glucose levels and insulin resistance index were significantly decreased while the disposition index, indicative of β-cell function and its capacity to compensate during insulin resistance, was increased in Gpr84−/− mice compared to WT mice." (PMID 32728158, 2020).
colitis (4 papers, 2022 to 2025). Inflammation of the colon. "Neut-c4, also prevalent in the early colitis phase, expressed genes associated with phagocytosis and reactive oxygen species (ROS) generation (Gngt2, Ltc4s, Gpr84)." (PMID 38674054, 2024). "Compared with WT mice, GPR84−/− mice developed significantly less severe colitis with reduced body weight loss and DAI." (PMID 34912006, 2022). "In both colon and peripheral blood leukocytes, GPR84 was significantly upregulated starting on day 4 and peaked on day 8, as compared to that on day 0, suggesting that increased GPR84 expression was associated with colitis." (PMID 34912006, 2022). "As GPR84 was highly upregulated in macrophages and affected macrophage polarization in the LP of the colitis mice, we performed double immunofluorescence staining for GPR84 and CD86 in colonic mucosa sections from patients and healthy controls." (PMID 34912006, 2022). "Together, these data demonstrate that blocking GPR84 with a small molecule antagonist protects against the intestinal mucosal inflammation in DSS-induced colitis, further confirming the involvement of GPR84 in IBD." (PMID 34912006, 2022). "Our data showed that knockout or blockade of GPR84 significantly reduced IL-1β level in both colitis mice and M1 macrophages, suggesting the possible involvement of NLRP3 inflammasome." (PMID 34912006, 2022). "CLH536, a novel GPR84 antagonist discovered by us, suppresses colitis by reducing the polarization and function of pro-inflammatory macrophages." (PMID 34912006, 2022). "GPR84 was found to be most significantly upregulated in CD11b+ macrophages (day 7), strongly suggesting a role of GPR84 in macrophages during colitis." (PMID 34912006, 2022). "Here we sought to study the role of GPR84 in colitis with GPR84−/− mice, a newly discovered GPR84 antagonist CLH536 and colon biopsy samples from UC and CD patients." (PMID 34912006, 2022). "Additionally, in a DSS-induced colitis model, Gpr84−/− mice reduced the infiltration of inflammatory cells and damage to the colonic mucosa." (PMID 39858878, 2025). "And the non-haematopoietic GPR84 showed little effect on colitis because the WT and GPR84−/− hosts received WT BM exhibited similar level of colitis with almost same body weight loss, DAI score and mucosal damage." (PMID 34912006, 2022). "Given that GPR84 may regulate colonic macrophage differentiation during colitis, we then studied whether GPR84 could affect macrophage polarization in vitro." (PMID 34912006, 2022). "However, the exact roles of GPR84 in inflammatory diseases such as colitis are still largely unclear and needed to be further explored." (PMID 34912006, 2022). "As GPR84 mediates the development of colitis in mice, we wondered whether GPR84 plays a similar role in IBD patients." (PMID 34912006, 2022). "As the knockout of GPR84 significantly alleviated the clinical symptoms of colitis in mice, we wondered whether a receptor antagonist may have similar effects." (PMID 34912006, 2022). "To investigate whether GPR84 is involved in the pathogenesis of colitis, we first checked the expression level of GPR84 on days 0, 2, 4, 6, and 8 in DSS-induced mouse model of acute colitis." (PMID 34912006, 2022). "We next sought to investigate whether GPR84 regulates macrophage population in colitis." (PMID 34912006, 2022). "Detailed expression analysis with quantitative reverse-transcription PCR revealed that GPR84 mRNAs were significantly upregulated in immune cells/tissues including peripheral blood leukocytes, spleen, and especially colonic LP at day 7 in DSS-induced colitis." (PMID 34912006, 2022). "GPR84 knockout (GPR84−/−) mice were generated with TALEN system and colitis was induced with DSS." (PMID 34912006, 2022).